DNAH3 (dynein axonemal heavy chain 3)
Description:
Force generating protein of respiratory cilia. Produces force towards the minus ends of microtubules. Dynein has ATPase activity; the force-producing power stroke is thought to occur on release of ADP. Involved in sperm motility; implicated in sperm flagellar assembly (By similarity). Essential for the assembly and structural organization of the sperm flagellum's axoneme, including its inner dynein arms and accessory components, which are critical for maintaining flagellar integrity and motility.
Synonyms: HsADHC3; DNAHC3B; DLP3; DKFZp434N074; DNAHC3-B; HDHC8; HEL-36
Tractability: Small molecule: a structure with a bound ligand is known. PROTAC: ubiquitination databases record sites on it.
Gene: Protein-coding gene on chromosome 16 (20,933,111 to 21,159,441, reverse strand). Ensembl gene ENSG00000158486.
Subcellular location: Cytoplasm, cytoskeleton, cilium axoneme; Cytoplasm; Cell projection, cilium, flagellum
Subcellular location (Human Protein Atlas): Mid piece; Principal piece; Equatorial segment; Flagellar centriole
Gene Ontology:
Molecular function: dynein intermediate chain binding; dynein light intermediate chain binding; microtubule motor activity; minus-end-directed microtubule motor activity; ATP binding
Biological process: inner dynein arm assembly; sperm axoneme assembly; cilium movement involved in cell motility; cilium-dependent cell motility; microtubule-based movement
Cellular component: cytoplasm; sperm flagellum; 9+2 motile cilium; axonemal dynein complex; inner dynein arm; axoneme; dynein complex; motile cilium
Genetic constraint (gnomAD): Loss-of-function variants: 307 observed, 404.39 expected, observed/expected ratio (o/e) 0.76, 90% interval 0.69 to 0.83. The upper end of that interval is the gene's LOEUF score, 0.83, which puts it in group 3 of 6, group 1 being the genes least tolerant of losing a copy. Missense variants: 4,623 observed, 5,111.2 expected, observed/expected ratio (o/e) 0.9, 90% interval 0.88 to 0.93. Synonymous variants: 1,887 observed, 1,915.6 expected, observed/expected ratio (o/e) 0.99, 90% interval 0.95 to 1.02.
Homologues: Orthologues: chimpanzee DNAH3 (99% identical), macaque DNAH3 (96% identical), rabbit DNAH3 (90% identical), pig DNAH3 (89% identical), dog DNAH3 (88% identical), rat Dnah3 (88% identical), mouse Dnah3 (88% identical), guinea pig DNAH3 (86% identical), tropical clawed frog dnah3 (75% identical), zebrafish dnah3 (67% identical), Drosophila melanogaster Dnah3 (48% identical). Paralogues in human: DNAH7 (51% identical), DNAH12 (50% identical), DNAH1 (40% identical), DNAH6 (35% identical), DNAH2 (34% identical), DNAH10 (31% identical), DNAH17 (30% identical), DNAH9 (30% identical), DNAH11 (30% identical), DNAH8 (29% identical), DNAH14 (29% identical), DNAH5 (29% identical), and 3 more.
Diseases named in the same sentence as DNAH3 in open-access papers:
DNAH3 is named in the same sentence as 18 diseases in open-access papers, as found by Europe PMC text mining. Sharing a sentence is not in itself a finding about the gene and the disease. The quoted sentences say what the papers report.
breast carcinoma (5 papers, 2018 to 2025). "It has been reported that mutations in DNAH3 are associated with lung, colon, and breast cancer." (PMID 38312775, 2024). "In addition, WES was performed on a Tunisian family with breast cancer, and the biological network construction and protein–protein interactions analyses showed that DNAH3 might be involved in breast cancer." (PMID 38312775, 2024). "Additionally, DNAH3 was identified as novel predisposition gene using exome sequencing in a Tunisian family with multiple non-BRCA breast cancer instances." (PMID 32778766, 2020). "Enriched biological process and protein–protein interaction networks resulted in the identification of four novel breast cancer candidate genes namely MMS19, DNAH3, POLK and KATB6." (PMID 29879995, 2018).
male infertility (4 papers, 2024 to 2025). The inability of the male to effect fertilization of an ovum after a specified period of unprotected intercourse. "We revealed that male infertility caused by DNAH3 mutations follows an autosomal recessive inheritance pattern, as confirmed through Sanger sequencing of the patients' families." (PMID 39503742, 2024). "This study revealed DNAH3 as a novel pathogenic gene of asthenoteratozoospermia, and the findings provide valuable suggestions for the clinical diagnosis and treatment of male infertility." (PMID 39503742, 2024). "The clinical phenotype of our patient is characterized by severe OAT, highlighting the potential application of assisted reproductive technologies, such as ICSI, in the treatment of male infertility associated with DNAH3 mutations." (PMID 39588341, 2024). "Collectively, these data demonstrate that DNAH3 defects contribute to male infertility associated with AT in both humans and mice." (PMID 38312775, 2024). "Our findings indicated that DNAH3 is a novel pathogenic gene for asthenoteratozoospermia and may further contribute to the diagnosis, genetic counseling, and prognosis of male infertility." (PMID 39503742, 2024). "Moreover, we suggest that ICSI might be a favorable treatment for male infertility caused by DNAH3 deficiency." (PMID 39503742, 2024). "This study provides an in-depth exploration of the complex relationship between biallelic mutations in the DNAH3 gene and the phenotype of OAT, a common form of male infertility." (PMID 39588341, 2024). "Currently, 13 members of the DNAH gene family have been reported, including DNAH1 to DNAH3, DNAH5 to DNAH12, DNAH14, and DNAH17, among which 11 genes (DNAH1, DNAH2, DNAH5 to DNAH12, and DNAH17) are associated with male infertility." (PMID 38312775, 2024). "Mutations of DNAH3 and DNAH12 are linked to male infertility and dynein dysfunction in humans." (PMID 40568142, 2025). "The DNAH3 gene will serve as a new indicator of pathogenic genes that have not received much attention in the field of male infertility." (PMID 39588341, 2024). "Our findings identify a function for DNAH3 in male reproduction in humans and mice and may provide a new view on the clinical practice of male infertility." (PMID 39503742, 2024). "However, the relationship between DNAH3 and male infertility is still unclear." (PMID 39503742, 2024). "However, whether DNAH3 is involved in male infertility remains unclear." (PMID 38312775, 2024). "Eleven of them have been found to be involved in male infertility, whereas the role of DNAH3 and DNAH14 in male infertility has not been clarified." (PMID 38312775, 2024).
Infertility (3 papers, 2021 to 2024). "In our study, bi-allelic variants of DNAH3 were identified in three infertile men and co-segregated with AT in the pedigree analysis." (PMID 38312775, 2024). "Herein, we identified biallelic variants of DNAH3 in four unrelated Han Chinese infertile men with asthenoteratozoospermia through whole-exome sequencing (WES)." (PMID 39503742, 2024). "In the present study, we identified pathogenic variants in DNAH3 in unrelated infertile men with asthenoteratozoospermia." (PMID 39503742, 2024). "In this study, we identified biallelic variants of DNAH3 (p.Gly1715Ser and p.Asp2493Asn, p.Phe2325Leu and p.Arg2991Cys, and p.Trp3420X and p.Arg3480Gln) in three unrelated infertile men whose spermatozoa displayed multiple morphological abnormalities of the flagella and decreased motility." (PMID 38312775, 2024). "Overall, these results indicate that ICSI may be an effective strategy for infertile men harbouring DNAH3 variants with AT to father offspring." (PMID 38312775, 2024). "Ultrastructural and mitochondrial defects in sperm from infertile men with DNAH3 variants." (PMID 39503742, 2024). "Taken together, these results demonstrate that biallelic DNAH3 variants may contribute to the AT phenotype in infertile men." (PMID 38312775, 2024). "Moreover, ICSI is as an optimized treatment for infertile men with DNAH3 variants." (PMID 39503742, 2024). "Moreover, the infertility of patients with DNAH3 variants and Dnah3 KO mice could be rescued by intracytoplasmic sperm injection (ICSI) treatment." (PMID 39503742, 2024). "We next examined the testis and epididymis of Dnah3 KO male mice to elucidate the etiology of infertility." (PMID 39503742, 2024). "Combined with the successful ICSI outcomes observed in Dnah3 KO mice, we suggest ICSI as an optimized treatment for infertile men carrying variants in DNAH3." (PMID 39503742, 2024). "Intriguingly, Dnah3 knockout (KO) male mice were also infertile, especially showing the severe reduction in sperm movement with the abnormal IDA and mitochondrion structure." (PMID 39503742, 2024). "ICSI was used to overcome the infertility of one patient and of the Dnah3 knockout mice." (PMID 38312775, 2024). "For example, Dnah3, is required to maintain sperm motility, without which Dnah3 mutants are infertile." (PMID 33535499, 2021).
Huntington disease (2 papers, 2020 to 2021). Huntington disease (HD) is a rare neurodegenerative disorder of the central nervous system characterized by unwanted choreatic movements, behavioral and psychiatric disturbances and dementia. "Additionally, the extensive alteration of apoptosis in severe WS is emphasized by the increased abundance of dynactin subunit 1 (DCTN1) coupled with decreased axonemal heavy chain 3 of dynein (DNAH3), highlighted in Huntington disease pathway." (PMID 32612536, 2020).
primary ciliary dyskinesia (2 papers, 2015 to 2022). A rare, genetically heterogeneous, primarily respiratory disorder characterized by chronic upper and lower respiratory tract disease. "Interestingly, a cluster formed by 12 elements, including WDR63, DNAH3, DNAI1, TTC18, SPAG17, TTC25, and CCDC113, was found to be a cluster related to primary ciliary dyskinesia and COPI-independent Golgi-to-ER (Cluster 10689, STRING False Discovery Rate: 1.0–12)." (PMID 36140829, 2022).
adenoma (1 paper, 2023). A neoplasm arising from the epithelium. "Interestingly, some mutations like KRAS and DNAH3 were detected in organoids but not in primary adenoma, and the multiple hit of FBXW7 was observed in O4, but only missense mutation was detected in P4." (PMID 37667332, 2023).
deafness (1 paper, 2019). An inherited or acquired condition characterized by the complete loss of the ability to hear from one or both ears. "Similarly, mutation of CG17150/Dnah3 caused deafness, but fertility appeared normal unless tested by a sperm competition assay." (PMID 30774648, 2019).
hearing loss (1 paper, 2023). "For example, DNAH3 is an outlier in metabolic hearing loss in the MUSC cohort and was also previously reported as associated with hearing loss, but in contrast it is an outlier in normal hearing in the Twins UK cohort." (PMID 38011198, 2023).
neuropathies (1 paper, 2020). "DNAH3 is a type of dynein involved in producing force for ciliary beating by using energy from ATP hydrolysis, and GOLGB1 is a widely expressed large coiled-coil protein and Golgi integral membrane protein associated with neuropathies." (PMID 33352926, 2020).
ovarian carcinoma (1 paper, 2021). A malignant neoplasm originating from the surface ovarian epithelium.
squamous cell carcinoma (1 paper, 2024). A carcinoma arising from squamous epithelial cells. "For example, DNAH3 is a commonly mutated gene in lung tumours, including adenocarcinomas and squamous cell carcinomas." (PMID 38312775, 2024).
cancer (5 papers, 2014 to 2024). A tumor composed of atypical neoplastic, often pleomorphic cells that invade other tissues. "However, we recommend that patients who carry variants in DNAH3 or other DNAH family genes should undergo regular check-ups and screening for early detection, and timely intervention if cancer is identified." (PMID 38312775, 2024).
Tumor (4 papers, 2012 to 2023). "Interestingly, three genes of the dynein family of microtubule-associated motor proteins (DNAH2, DNAH3 and DNAH5) showed stopgain mutations in different post-chemotherapy residual tumor samples." (PMID 38254917, 2023).
neurodevelopmental disorder (2 papers, 2025 to 2026). A behavioral and cognitive disorder with onset during the developmental period that involves impaired or aberrant development of intellectual, motor, or social functions. "The top candidate genes include both genes previously implicated in neurodevelopmental disorders (e.g., ZNF774 and DNAH3) and genes not previously reported but with strong evidence of being involved in neurodevelopmental phenotypes." (PMID 40386381, 2025).
DNAH3 also shares sentences with these, for which no sentence is quoted: acute myeloid leukemia (1 paper); adenocarcinoma (1); familial breast cancer (1); oligoasthenoteratozoospermia (1).